S100B (S100 calcium binding protein B)
Diseases named in the same sentence as S100B in open-access papers (continued):
Sharing a sentence is not in itself a finding about the gene and the disease.
ischemic stroke (continued). "The S100B protein typically reaches its peak concentration on day 2 or 3 after ischemic stroke onset, whereas among ICH patients, it has been shown that there is a rapid increase in plasma S100B levels within a few hours." (PMID 37892701, 2023). "In a previous study, among the blood samples obtained within 6 h after ictus (n = 337), S100B levels were significantly higher in ICH patients (107.58 vs. 58.70 pg/mL; p < 0.001) compared to those with ischemic stroke." (PMID 37892701, 2023). "The ischemic stroke was induced by photothrombosis in the cerebral cortex of SCID mice in which the ischemic cavity was surrounded by GFAP+ and S100β+ glial scar at day 14 and the cortex collapsed at day 30 without treatment." (PMID 37867250, 2023). "Another panel of 5 markers, consisting of S100B, vWF, MMP9, B-type neurotrophic growth factor (BNGF), and monocyte chemoattractant protein 1 (MCP1), can distinguish patients with ischemic stroke from healthy controls with 92% sensitivity and 93% specificity." (PMID 36313479, 2022). "As a predictor of a hemorrhagic transformation in ischemic stroke patients, the CLDN5/ZO1 ratio had the highest sensitivity and an even higher specificity than S100B." (PMID 36293204, 2022). "Published studies have paid little attention to the correlations between Lp-PLA2 activity (or mass) and other ischemic stroke biomarkers, including CRP, MMPs, IL-6, TNF-α, VCAM1, ICAM1, S100B, vWF, BNGF, and MCP1." (PMID 36313479, 2022). "S100B correlated with neurological deficits in ischemic stroke and TBI; S100B temporal profile in ischemic stroke was different compared to TIA or TBI." (PMID 33115334, 2021). "A related panel of S100B, MMP-9, vWF, and vascular cell adhesion molecule (VCAM) studied by the same group of researchers in 65 suspected ischemic stroke patients and 157 controls within 24 h of symptoms provided a sensitivity and specificity of 90%." (PMID 33633673, 2021). "The strengths of this study are the short median time interval between ischemic stroke debut and blood sampling (<8 h), the sampling of blood prior to thrombolysis, the discrimination of ischemic stroke from TIA patients, and the inclusion of IL-6 and S100B." (PMID 32595585, 2020). "Despite this variability, single S100B concentrations measured 2-3 days after non-lacunar ischaemic stroke were found to provide optimal predictive value compared to more complex measures." (PMID 21034449, 2010). "Decreases LDH activity and MDA, NSE and S100β contents; relaxes the cerebral basilar artery in a dose-dependent manner; up-regulates IP3, PKC, TRPV4, SKca and IKca expression; reduces Ca2+ fluorescence intensity; and ameliorates brain injury in rats with ischaemic stroke." (PMID 35566359, 2022). "In addition, in S100B knockout mice, where the protein was not synthesized, functional and neuropathological ameliorations were observed after traumatic brain injury, and similar results were observed in rats with ischemic stroke silenced for S100B using RNA interference." (PMID 37298554, 2023). "A multicentre study focusing on S100β protein, NSE, GFAP and activated protein C–protein C inhibitor complex demonstrated the ability of GFAP to differentiate haemorrhagic stroke from ischaemic stroke, which has not been observed for other proteins." (PMID 25029344, 2014). "GFAP, but not S100B or NSE, allowed to differentiate between ICH and ischemic stroke." (PMID 33115334, 2021).
schizophrenia (63 papers, 2009 to 2026). A major psychotic disorder characterized by abnormalities in the perception or expression of reality. "Increased concentrations of serum S100β are also associated with psychotic features of schizophrenia and depressive features in major depression disorder." (PMID 33139732, 2020). "S100B has been implicated in the pathology of schizophrenia as a marker of astrocytic response and BBB dysfunction." (PMID 32439851, 2020). "Levels of plasma autoimmune and anti-inflammatory markers are associated with the levels of S100B in patients with schizophrenia." (PMID 27279465, 2016). "In humans, high levels of S100B have been associated with schizophrenia and other brain-related diseases." (PMID 27507242, 2016). "This suggests involvement of S100B in an ongoing and dynamic process associated with structural brain changes in schizophrenia." (PMID 27013967, 2016). "The most important result of this study is that the level of TGF-β1, IL-23 and IL-10 were independently associated with plasma levels of S100B in patents with schizophrenia." (PMID 27279465, 2016). "In post-mortem brains of schizophrenia subjects, S100B-immunoreactive astroglia are found in areas implicated in schizophrenia, including anterior cingulate cortex, dorsolateral prefrontal cortex, orbitofrontal cortex and hippocampi." (PMID 23547920, 2013). "This current study showed that levels of S100B are raised in female patients diagnosed with schizophrenia and correlate with BMI, which is possibly linked to higher levels of release from adipocytes." (PMID 23705829, 2013). "Genetic polymorphisms in S100B and receptor for advanced glycation end-product genes in schizophrenia cohorts suggest these abnormalities are likely primary/pathogenic rather than secondary/biomarkers." (PMID 23547920, 2013). "Two Chinese studies have investigated S100B gene polymorphisms as possible indicators of susceptibility to schizophrenia." (PMID 24358202, 2013). "In schizophrenia, increased S100B levels, as well as associations with acute positive and persisting negative symptoms, have been reported." (PMID 24358202, 2013). "In agreement with these arguments genetic studies demonstrated that S100B is a susceptibility gene for mood disorders and schizophrenia, developmental dyslexia and cognitive dysfunction." (PMID 22916238, 2012). "A novel finding in this study is that S100B appears to be a marker of severity of risk of suicidality in patients with mood disorders and schizophrenia." (PMID 20559426, 2010). "Our data support the use of S100B as an adjunctive biomarker to assess suicidal risk in patients with mood disorders or schizophrenia." (PMID 20559426, 2010). "With these facts in mind, we hypothesized that inflammatory markers are independently associated with the concentrations of S100B in schizophrenia patients." (PMID 27279465, 2016). "The ROC curves analysis revealed that the area under the curve (AUC) was 0.666 (95% confidence interval = 0.536–0.795; p = 0.015), when assessment the diagnostic accuracy of the plasma S100B concentration of comparison between patients with schizophrenia and healthy controls." (PMID 27279465, 2016). "Due to its functions, trophic actions on neurons and astrocytes and involvement in inflammatory response, S100B seems to be linked to neurodevelopemental and inflammatory hypothesis of schizophrenia pathogenesis." (PMID 25202915, 2014). "In summary, it remains unclear whether S100B elevation is associated with schizophrenia, and if so, whether the association reflects the consequence of acute or chronic disease processes, compensatory mechanisms or genetic risk for schizophrenia." (PMID 24358202, 2013). "Interestingly, schizophrenia is indeed associated with certain haplotypes, leading to an increased S100B expression, and postmortem studies are suggestive of a progressive reduction of neuropil." (PMID 20631894, 2010).
schizophrenia (continued). "Interestingly, overweight, visceral obesity, and insulin resistance may be associated with S100B levels in patients with schizophrenia." (PMID 38783266, 2024). "Moreover, S100B SNPs are significantly associated with several neuropathological and psychiatric disorders, such as Parkinson's disease, depressive disorder, schizophrenia, stroke and dementia." (PMID 33982673, 2021). "The animal experiment has showed that the transgenic mice with the overexpression of S100B would display the deficiency of learning ability and behavior disorder, suggesting that the potential relationship between the S100B and the positive symptoms of schizophrenia." (PMID 28373983, 2017). "Furthermore, certain neuropsychiatric disorders, among them schizophrenia, have been found to be associated with elevated serum and cerebrospinal fluid (CSF) levels of S100B, thus implying immunoreactive glial processes as important in either their genesis or progression." (PMID 26941608, 2016). "Also, a S100B gene haplotype involved in increased S100B expression is associated with schizophrenia, so levels of S100B could be expected to be altered in schizophrenia, either primary or secondary to the disease." (PMID 25202915, 2014). "S100B may however become an important risk stratification tool for the assessment of suicidality in patients with severe mental disorders such as mood disorders and schizophrenia." (PMID 20559426, 2010). "Increased cerebrospinal fluid levels of S100B have also been reported in PD, AD, and schizophrenia, implying roles for S100B in the pathogenesis of neurodegenerative diseases." (PMID 40981102, 2025). "In schizophrenia, S100B is also increasingly recognized as a relevant biomarker and potential contributor to disease pathophysiology." (PMID 40650013, 2025). "Studies have reported elevated S100B levels in both serum and cerebrospinal fluid in patients with schizophrenia, reflecting glial pathology and potential BBB alterations." (PMID 40650013, 2025). "S100B plasma levels after 6–8 weeks of treatment with antipsychotics showed a negative correlation with the number of suicide attempts in early onset schizophrenia-spectrum adolescents." (PMID 37759935, 2023). "Comparing circulating S100B levels between schizophrenia patients and matched healthy controls (HC), most studies reported elevated S100B, either in chronic or first-episode SCH." (PMID 37759935, 2023). "Meta-analyses were performed for schizophrenia, mood disorders, and autism spectrum disorder, showing elevated S100B concentrations in the studied illnesses." (PMID 37759935, 2023). "A previous study showed a diurnal variation in serum S100B concentrations in patients with acute paranoid schizophrenia." (PMID 35743957, 2022). "This indicates that the functional changes of the S100B protein in the dorsolateral prefrontal cortex are very important to the etiology of schizophrenia." (PMID 35743957, 2022). "In the follow up, researchers need to conduct basic research on various types of schizophrenia and S100B." (PMID 35743957, 2022). "Compared to mental health controls, S100B in the nuclear proteome of the corpus callosum from schizophrenia patients was weakened via mass spectrometry." (PMID 35743957, 2022). "Preclinical studies and clinical reports suggested that a higher concentration of S100B in the peripheral blood and cerebrospinal fluid was found in patients with schizophrenia when compared with control." (PMID 35743957, 2022). "Cognitive impairments in schizophrenia are associated with neuroinflammatory markers such as CRP, S100B and neuron-specific enolase, and with lower concentrations of BDNF." (PMID 34025476, 2021). "PANSS total score was significantly and positively correlated with CSF HGF and S100B levels in patients with schizophrenia {r = 0.34, p = 0.001 (significant even after correction) and r = 0.28, p = 0.007}." (PMID 32439851, 2020).
schizophrenia (continued). "The level of S100B in serum correlates with the development of insulin resistance in patients with schizophrenia." (PMID 32116664, 2019). "The glial theory of schizophrenia based on the proven inflammatory response and elevated levels of the characteristic markers of active glia—S100B and glial fibrillary acidic protein (GFAP)." (PMID 32116664, 2019). "The levels of the astrocyte markers (GFAP, S100B) were increased unevenly in patients with schizophrenia." (PMID 32116664, 2019). "As Streitbürger and Schmitt have pointed out, S100B elevation in schizophrenia is within the nanomolar range." (PMID 28358925, 2017). "It has been reported that S100B exerts toxic effects on neurons in schizophrenia by inducing neuronal apoptosis via mechanisms involving RAGE-dependent overproduction of neuroinflammatory mediators." (PMID 28373983, 2017). "Elevated S100B levels in the blood, CSF, and brains of individuals with schizophrenia are considered to be neurobiological consequences of glial activation and/or injury associated with BBB and blood–CSF hyperpermeability." (PMID 28588507, 2017). "In line with the proinflammatory actions of the S100B-RAGE axis, strong evidence is implicating elevated serum and CSF levels of S100B in the psychopathology of schizophrenia." (PMID 28373983, 2017). "Increased S100B levels in the early stages of schizophrenia support the idea of neurodegenerative process and anti-psychotics such as haloperidol and clozapine have been shown to decrease S100B release from glial cells." (PMID 28870209, 2017). "First, the meta-analysis by Aleksovska and colleagues, which included our original study, did find elevated S100B blood levels in schizophrenia." (PMID 28358925, 2017). "Here, we conducted a systematic and quantitative meta-analysis of changes in serum S100B in schizophrenia, which extends former meta-analyses on this issue by including further studies and accordingly, increasing statistical power and evidence." (PMID 26941608, 2016). "In conclusion, findings of our study demonstrate high levels of plasma S100B in patients with schizophrenia." (PMID 27279465, 2016). "In summary, our comprehensive meta-analysis including 19 original studies with a total of 766 patients and 607 healthy control subjects confirms higher values of the glial serum marker protein S100B in schizophrenia compared to control subjects." (PMID 26941608, 2016). "A multiple meta-regression analysis including illness duration and age at onset confirmed the impact of the first factor on serum S100B in schizophrenia." (PMID 26941608, 2016). "In conclusion, duration of illness seems to influence serum S100B levels in schizophrenia patients, with larger differences between patients and control subjects the longer the disorder has been present on average." (PMID 26941608, 2016). "We found that concentrations of S100B were elevated in schizophrenia patients than healthy participants (p < 0.05), and were negatively related with the severity of symptoms (p = 0.046)." (PMID 27279465, 2016). "The meta-analysis confirmed higher values of the glial serum marker S100B in schizophrenia if compared with control subjects." (PMID 26941608, 2016). "From results of our ROC curve analysis, when 144.46 pg/ml was used as the cut off value of the level of S100B, we found high sensitivity (97.6%), but low respecity(36.4%) of plasma concentrations of S100B for the diagnosis of schizophrenia." (PMID 27279465, 2016). "Across all included studies comparing patients suffering from schizophrenia with control subjects, Hedges’ g amounted to 0.925, indicating a higher level of S100B in schizophrenia patients compared to healthy controls." (PMID 26941608, 2016). "Previous studies found higher S100B serum levels in patients with schizophrenia compared to healthy controls, and a number of covariates influencing the size of this effect have been proposed in the literature." (PMID 26941608, 2016).
schizophrenia (continued). "Here, we conducted a meta-analysis and meta-regression analysis on alterations of serum S100B in schizophrenia in comparison with healthy control subjects." (PMID 26941608, 2016). "The sensitivity and specificity of S100B for the diagnosis of schizophrenia were 97.6% and 36.4%, respectively, when using 144.46 pg/ml as the cut-off value for the plasma S100B concentration." (PMID 27279465, 2016). "Receiver operating characteristic (ROC) curve analysis showed that different S100B levels between schizophrenia and healthy participants can be used as a clinical diagnostic factor (predictive value: 0.666, p = 0.015)." (PMID 27279465, 2016). "In order to analyze the influence of medication on serum S100B levels in schizophrenia there are generally two options." (PMID 26941608, 2016). "Further, increased cerebrospinal fluid levels of S100B have been also reported in Parkinson’s disease, AD, and schizophrenia, implying roles for S100B in the pathogenesis of neurodegenerative diseases." (PMID 26733811, 2015). "Positive correlation of serum S100B with BMI was previously reported in a combined sample of cognitively intact lean and obese subjects and in subjects with schizophrenia." (PMID 26500502, 2015). "Schizophrenia patients showed 76% higher S100B blood levels than controls with mMR = 1.76 95% CI: 1.44–2.15." (PMID 25202915, 2014). "In order to assess the relationship between circulating blood levels of S100B and schizophrenia, we carried out a systematic review and meta-analyses of case-control studies on this topic." (PMID 25202915, 2014). "During the last twenty years the S100B protein has gained attention in the research area for peripheral biomarkers of schizophrenia." (PMID 25202915, 2014). "S100B in peripheral blood was significantly increased in schizophrenia patients, with an almost double level in cases than controls." (PMID 25202915, 2014). "Description of the studies comparing blood levels of S100B in schizophrenia patients and controls, included in the meta-analysis." (PMID 25202915, 2014). "Taken together, the data suggested that levels of S100B are altered in schizophrenia and these levels are also likely related to patients BMI, in addition to astrocyte dysfunction." (PMID 23705829, 2013). "Previous studies have however reported that levels of S100B in drug naive patients with schizophrenia are raised." (PMID 23705829, 2013). "A number of previous studies have suggested that the levels of S100B protein are altered in patients with schizophrenia, with the general observation that S100B levels are increased." (PMID 23705829, 2013). "Meta-analysis (12 studies, 380 schizophrenia, 358 healthy controls) confirmed elevated serum S100B levels in schizophrenia." (PMID 23547920, 2013). "Elevated serum S100B in schizophrenia has been fairly consistently reported since the first publication more than a decade ago, and has been confirmed by a meta-analysis." (PMID 24358202, 2013). "In order to determine changes in S100B levels in patients diagnosed with schizophrenia, the demographics of control and patient cohorts were initially analysed." (PMID 23705829, 2013). "In closing, while a number of studies have demonstrated that levels of S100B are altered in schizophrenia, many of these reports are contradictory when suggesting that age, gender, medication and illness severity all have an impact (or not) on S100B levels." (PMID 23705829, 2013). "Here, a study to further investigate the role of S100B in schizophrenia was conducted comparing patients treated with clozapine and healthy controls." (PMID 23705829, 2013). "Another limitation of this study is the direct comparison of S100B levels between patients on medication and drug naive patients with schizophrenia." (PMID 23705829, 2013).